PDPN (podoplanin)
Diseases named in the same sentence as PDPN in open-access papers (continued):
Sharing a sentence is not in itself a finding about the gene and the disease.
tumor (continued). "In tumor tissues, CD4 and CD8 T cell markers (present in TSE-positive; nearly absent in TSE-negative samples) showed an inverse relationship with PDPN expression (nearly absent in TSE-positive; present in TSE-negative samples)." (PMID 38355607, 2024). "Fibroblast activation markers FAP, CD29, αSMA, PDPN, CD90, FSP1 and PDGFRβ expression levels were determined and compared for tumour and non-cancerous adjacent lung tissue from NSCLC patients by looking at the percentage positivity for each marker." (PMID 38582812, 2024). "Tumor-bearing mice had increased levels of PDPN in plasma, and CLEC-2 depletion suppressed venous thrombosis in tumor-bearing but not tumor-free mice." (PMID 40741180, 2024). "Among the markers of vascular origin, podoplanin was negative in all cases, while CD34 was positive in most cases (n = 7), with weak (n = 1) or moderate (n = 6) immunostaining in 5–30% of the tumor cells (average value of 10%)." (PMID 39451657, 2024). "The recombinant mouse IgG2a-type PMab-117 (PMab-117-mG2a) reacted with the PDPN-positive tumor PC-10 and LN319 cells but not with PDPN-knockout LN319 cells in flow cytometry." (PMID 39594582, 2024). "In lung adenocarcinoma (LUAD), LVD is higher in the tumor stroma of PNPD + tissue, while in lung squamous cell carcinoma (LSCC), podoplanin does not promote cell migration, but also down-regulates VEGF-C by regulating JNK pathway." (PMID 38566083, 2024). "Immunohistochemically, the tumor cells were positive for ERG, CD34, factor VIII-related antigen, and CD31, and negative for podoplanin (D2-40) and α-smooth muscle actin, indicating pure vascular endothelial differentiation." (PMID 37027101, 2023). "Within KPR tumours, LRRC15 expression was restricted to PDPN+ fibroblasts and largely absent in other compartments." (PMID 36171287, 2022). "Immunohistochemically, the tumor was positive for S-100 and cluster of differentiation CD99 in the sarcomatous component, but negative for CD 34, calretinin, STAT6, D2-40 (podoplanin), and cytokeratin." (PMID 36451398, 2022). "We quantified percentages of Ki67+ and podoplanin+ cells among EGFP+ cell populations in nontumor and tumor tissues." (PMID 33863879, 2021). "In this study, we present a potential novel mechanism of lymphatic metastasis in OSCC—lymphatic mimicry (LM), a process whereby tumour cells form cytokeratin+/LYVE-1+, but podoplanin-negative, mosaic endothelial-like vessels." (PMID 33674563, 2021). "Likewise, when we explored the effects of IL1β-silenced tumor cells on co-cultured NCFs, we could observe that cocultured fibroblasts lost the expression of inflammatory cytokines, as IL6, LIF or CCL2, while acquired markers of myofibroblasts (ACTA2, PDPN, MYH11, or CNN1)." (PMID 34066976, 2021). "While neither body weight nor tumor weight showed statistical difference between the control and the DDR1-IN-1 mice, results of the CDH1/PDPN dual immunohistochemical stained sections from two groups were distinct." (PMID 32244515, 2020). "In the extraocular tumor component, all tumors of that study showed subconjunctival peritumoral vessels that were LYVE-1 (+) and podoplanin (+), but notably no intratumoral recruitment was observed." (PMID 30781402, 2019). "These activated CAF-like cells promoted in vivo tumor growth and enhanced the number of CSCs in a non-SCLC cell line, and all these effects were podoplanin-dependent." (PMID 30736372, 2019). "PDPN was induced by hypoxia and its overexpression undergoes a reduction of adhesion, making it an anti-adhesion molecule in the absence of CCL21, in the tumor." (PMID 28416768, 2017). "The presence or absence of lymphatics in the primary tumours was assessed by immunohistochemical expression of LYVE-1 and podoplanin." (PMID 22612847, 2011). "PDPN may be an attractive target to simultaneously reduce VTE and tumor progression in some types of cancer, perhaps without increasing the risk of bleeding." (PMID 40741180, 2024).
tumor (continued). "The negative prognostic impact of podoplanin expression in PDAC has been documented previously and podoplanin-positive stromal cells enhance invasion and proliferation of tumor cells." (PMID 37350578, 2023). "In our study, lymphatic podoplanin deletion and consequential reduction in MSMs did not impact on primary B16F10 tumor growth, which is in contrast to the complete deletion of both MSMs and subcapsular sinus macrophages (SSMs) using CD169-DTR mice that exacerbated primary tumor growth." (PMID 35892863, 2022). "Immunohistochemistry for the pan-CAF marker, podoplanin (PDPN), revealed no significant increase in the number of CAFs in tumours following irradiation, which was consistent with similar levels of collagen deposition in irradiated KPC tumours compared with those in KPC control tumours." (PMID 38421046, 2024). "Therefore, podoplanin, along with other growth factors and proteins, may play a role in increasing the epithelial proliferative activity and the invasiveness and recurrence of OKC after treatment, making it resemble a neoplasm rather than a cystic lesion." (PMID 38962078, 2024).
cancer (388 papers, 2005 to 2026). A tumor composed of atypical neoplastic, often pleomorphic cells that invade other tissues. "The Akt/NF‐κB pathway was significantly activated in podoplanin (PDPN)(+) cancer‐associated fibroblasts (CAFs)." (PMID 39764562, 2025). "Podoplanin-expressing cancer-associated fibroblasts (CAFs) are associated with cancer cell proliferation, invasion, and metastasis in several types of tumors." (PMID 41511312, 2025). "Cluster k15–04 showed high CD90 and podoplanin expression, indicative of cancer-associated fibroblasts (CAFs), andaSMA expression." (PMID 39698899, 2025). "In most cancers, high PDPN expression in CAFs is associated with poor patient outcomes, including lymph node metastasis and reduced overall survival." (PMID 40842027, 2025). "Podoplanin (PDPN), a transmembrane receptor glycoprotein upregulated in cancer-associated fibroblasts and inflammatory macrophages, contributes to the formation and maturation of TLSs23." (PMID 39827246, 2025). "We assessed stromal integrity using alpha smooth muscle actin (αSMA) and podoplanin (D2-40) staining to identify cancer associated fibroblasts (CAFs) and CD31 for endothelial cells." (PMID 40410344, 2025). "Cancer-associated fibroblasts express podoplanin protein, which triggers platelet activation and aggregation via C-type lectin receptor 2 (CLEC-2)." (PMID 39759851, 2025). "Specifically, S100A4 and PDPN are proteins that exhibit high expression in cancer-associated fibroblasts, while Cytokeratin (CK) stains the epithelial regions and DAPI stains adenine–thymine-rich regions in DNA." (PMID 41073772, 2025). "We identified podoplanin (PDPN)‐positive cancer‐associated fibroblasts, and CD45+ immune cells had the highest levels of IL‐6 and that CD45+ immune cells were the most abundant cell population quantified." (PMID 38632714, 2024). "High PDPN expression in cancer cells induced platelet aggregation and was associated with an increased risk of venous thromboembolism (VTE) and poor prognosis." (PMID 38504248, 2024). "Such PDPN-associated mechanisms underlying VTE in patients with GBM highlight the potential implications for cancer-associated venous thrombosis." (PMID 39682237, 2024). "PDPN‐positive cancer‐associated fibroblasts have been implicated with immune suppression in pancreatic adenocarcinoma and lung cancer." (PMID 38470096, 2024). "The other subset presented the characterization of cancer-associated fibroblasts (CAFs), expressing markers such as PDPN and PDGFRB." (PMID 36646679, 2023). "In the current study, we demonstrated that podoplanin-positive cancer-associated fibroblasts (PDPN+ CAFs) were correlated with poor prognosis in OSCC." (PMID 37993428, 2023). "PDPN expression is strongly enhanced on cancer-associated fibroblasts in PDAC and high expression levels are correlated with poor prognosis in some, but not all, studies." (PMID 37350578, 2023). "Studies have consistently demonstrated that increased expression of podoplanin is associated with angioinvasion in various types of cancers, including PTC." (PMID 38089632, 2023). "PDPN overexpression has been linked to cell migration, cell adhesion and cytoskeletal contractility in cancer cells." (PMID 37161290, 2023). "We further explored the role of PDPN in the crosstalk between GC cells and cancer associated fibroblasts (CAFs)." (PMID 36156321, 2023). "Among these, D2-40, a podoplanin-specific antibody that highlights lymphatic endothelial cells in normal tissues, vascular neoplasias, and carcinoma-associated endothelial and epithelial cells, has demonstrated good utility and main diffusion." (PMID 36979946, 2023). "Podoplanin expression is associated with myofibroblast phenotypes and upregulated during inflammation and cancer." (PMID 36278174, 2022). "In head and neck cancer, PDPN is a marker of lymphatic vessels; in predicting cancer progress risk, it was correlated with metastasis, recurrence, and poor clinical prognosis of patients with HNSCC." (PMID 36077194, 2022).
cancer (continued). "Cancers in which high levels of podoplanin are expressed are associated with an increased risk of developing cancer-associated thrombosis, the most common cause of cancer-related death after cancer itself." (PMID 36361963, 2022). "In summary, in this study we elucidate, to our knowledge for the first time, the cell surface interactome of an understudied cancer-associated protein, PDPN." (PMID 34879110, 2021). "In cancer patients, the endogenous ligand podoplanin binds to C-type lectin-like receptor 2 to induce platelet activation, promoting hematological cancer metastasis and cancer associated thrombosis." (PMID 35003363, 2021). "The cancer-associated fibroblast (CAF) marker podoplanin (PDPN) is generally correlated with poor clinical outcomes in cancer patients and thus represents a promising therapeutic target." (PMID 34879110, 2021). "The authors demonstrated that podoplanin-positive cancer-associated fibroblasts (CAFs) mixed with NSCLC PC-9 cells allowed the generation of round and steric aggregates (hybrid cancer organoids)." (PMID 33445709, 2021). "Collectively, these studies confirmed that NIR-PIT with NZ-1-IR700 can cause necrotic cell death, universally for MPM cancer cells with PDPN expression." (PMID 32326079, 2020). "Key words:Cancer-associated fibroblasts, myofibroblasts, head and neck neoplasms, podoplanin, immunohistochemistry." (PMID 31967978, 2020). "In them, CAFs presented elevated RAMP3 and podoplanin (PDPN), a marker of lymphatic endothelial cells and lymphangiogenesis associated with a poor prognosis in various types of cancers." (PMID 33489885, 2020). "PDPN has been assumed as one of the candidate markers of cancer stem cells, associated with cancer cell invasion or migration, as well as the prognosis of specific squamous cancers." (PMID 32408907, 2020). "PDPN has been recently reported to be expressed in not only cancer cells but also cancer-associated fibroblasts (CAFs) of various malignant tumors." (PMID 32326079, 2020). "PDPN-positive cancer-associated fibroblasts (CAFs) contributed to an essential role in primary resistance to epidermal growth factor receptor tyrosine kinase inhibitors (EGFR-TKI)." (PMID 33123464, 2020). "A subsequent number of studies have revealed increased expression of podoplanin by CAFs and its association with tumor progression, metastasis in various cancers, such as breast, lung, colorectal and esophageal cancers." (PMID 31137693, 2019). "PDPN is considered as a specific lymphatic vessel marker, and since lymphangiogenesis levels are correlated with poor prognosis in cancer patients, it is proposed as a diagnostic marker." (PMID 31195298, 2019). "All these findings enlighten the podoplanin–CLEC-2 axis as a novel therapeutic target for treatment of cancer and its associated thromboembolism." (PMID 30736372, 2019). "Human PDPN (hPDPN) is expressed in many malignant tumors, including brain tumors and mesotheliomas, and is associated with malignant progression and cancer metastasis." (PMID 31061899, 2019). "A few reports detected enhanced expression of soluble podoplanin in biological fluids of cancer patients associated with poor prognosis." (PMID 30736372, 2019). "For instance, CD44 reportedly interacts with podoplanin to promote cellular protrusions and provide directional cues in cancer-associated epithelial cells." (PMID 30745334, 2019). "Podoplanin has previously been reported to enhance the migration of cancer-associated MSC lines, and, where analysed, MSCs and ECs associated with with specialised lymphoid tissues." (PMID 30745334, 2019). "Gain- and loss-of-function experiments suggest that podoplanin cooperates with CD44 to promote directional migration of carcinoma cells." (PMID 30736372, 2019). "Further, a high expression of PDPN has also been observed in cancer-associated fibroblasts (CAFs) of the stroma surrounding tumors." (PMID 29765527, 2018).
cancer (continued). "The overexpression of PDPN in cancers is associated with hematogenous metastasis by interactions with the C-type lectin-like receptor 2 (CLEC-2)." (PMID 30362926, 2018). "Expression of CD42b, a platelet marker, was observed around cancer-associated fibroblasts (CAFs) in the biopsy specimens and podoplanin expression was found on the membranes of CAFs." (PMID 28449652, 2017). "First, when IDC and DCIS were analyzed by immunohistochemistry according to the presence of podoplanin-expressing cells, the numbers of cancer-associated fibroblasts with high expression of this glycoprotein were significantly higher in IDC than in DCIS cases." (PMID 28938000, 2017). "Podoplanin expression can be used as a predictor of the risk of cancer development in oral precancerous lesions." (PMID 28855922, 2016). "PDPN is also expressed by inflammatory macrophages as well as cancer-associated fibroblasts of various malignancies." (PMID 26893367, 2016). "We previously named PDPN as "Aggrus" because PDPN possesses a platelet aggregation-inducing activity, which is associated with cancer metastasis." (PMID 27031228, 2016). "Based on the current study and the concept of rational drug design, a series of derivatives of 2CP can be synthesized to further improve the inhibitory efficacy of 2CP on PDPN-induced platelet aggregation associated with cancer growth and metastases." (PMID 26528756, 2015). "Podoplanin expression in cancer cells or cancer-associated fibroblasts was reported to be involved in poor prognosis of several cancers." (PMID 25723283, 2015). "It has become very clear that PDPN acts as an important effector of signaling events that underlie cancer progression." (PMID 25826087, 2015). "Recent data from studies of various human cancer types suggest a possible association of podoplanin expression with invasion and metastasis of tumors." (PMID 24551781, 2012). "Recent studies have shown that overexpression of podoplanin is associated with metastasis and survival in patients with several cancer types." (PMID 22580922, 2012). "The glycoprotein podoplanin is upregulated in the invasive front of several human cancers and has been associated with epithelial-mesenchymal transition, increased cell migration and tissue invasion." (PMID 21385358, 2011). "There are a few studies indicating increased podoplanin expression in fibroblasts in reactive tissues, such as in chronic pleuritis, in cancer-associated fibroblasts and in cultured fibroblasts." (PMID 21385358, 2011). "In this review, we will focus on the molecular basis underlying the phenomenon of cell invasion induced by podoplanin, and discuss potential implications for cancer diagnosis and treatment." (PMID 17179989, 2007). "It is known that tissue factor (CD142) and podoplanin‐expressing EVs contribute to cancer‐associated thrombosis; however, a comparison of the gold standard anticoagulant effect of such mechanisms is unknown." (PMID 40292918, 2025). "Moreover, NIR-PIT induced death in PDPN-expressing cancer cells and cancer-associated fibroblasts, leading to an increase in the number of cytotoxic T cells in tumor tissue." (PMID 41011286, 2025). "Moreover, our data showed that high macrophage density, particularly of the M2-like subtype, is locally associated with increased stromal PDPN expression, which in turn correlates with more advanced cancer stages and reduced relapse-free survival." (PMID 40842027, 2025). "However, several studies have linked PDPN and macrophages to stimulate lymphangiogenesis to facilitate the recruitment of lymphocytes in inflamed tissues caused by infection, cancer or chronic inflammation." (PMID 39355243, 2024).